ORM2 (orosomucoid 2)
Diseases named in the same sentence as ORM2 in open-access papers (continued):
Sharing a sentence is not in itself a finding about the gene and the disease.
Obesity (1 paper, 2024). Accumulation of substantial excess body fat. "Crucially, genetic association studies in humans identified an obesity‐associated Orm2 variant (D178E), which shows decreased GP130/IL23R binding and impaired browning capacity in mice." (PMID 39248328, 2024). "While these results indicate a potential functional impact of the Orm2‐D178E variant, it is important to note that the current GWAS data do not show a statistically significant association between this SNP and obesity." (PMID 39248328, 2024). "Therefore, further research with larger cohorts and more detailed phenotypic analyses is necessary to fully understand the role of Orm2 genetic variants in human metabolic traits and obesity." (PMID 39248328, 2024). "Liver‐secreted Orm2 promoted thermogenesis in BAT and scWAT via p38 through binding to cell surface GP130/IL23R and administration of Orm2 ameliorated HFD‐induced obesity in vivo." (PMID 39248328, 2024). "Future clinical studies are needed to explore the therapeutic potential of Orm2 for the treatment of obesity in humans." (PMID 39248328, 2024). "Although the association between rs1826232 with obesity is not significant enough to reach p value<0.05, we demonstrated that Orm2‐D178E compromised its function to ameliorate high‐fat‐diet‐induced obesity." (PMID 39248328, 2024). "Overall, the research identifies Orm2 as a promising therapeutic target for obesity, mediating adipose browning through the GP130/IL23R‐p38 signalling pathway." (PMID 39248328, 2024). "Notably, in the context of obesity, Orm2, but not a GP130/IL23R‐binding deficient mutant of Orm2, is capable of inducing thermogenesis." (PMID 39248328, 2024). "Nevertheless, the potential involvement of Orm2 in thermogenic regulation as a means to counteract obesity has not yet been fully established." (PMID 39248328, 2024). "Notably, recombinant Orm2 but not the IL23R/GP130‐binding mutant form ameliorated HFD‐induced obesity." (PMID 39248328, 2024).
prostate carcinoma (1 paper, 2024). A carcinoma that arises from epithelial cells of the prostate gland. "ORM2 is involved in acute inflammatory responses, a potential marker for diagnosis of prostate cancers." (PMID 38029961, 2024).
steatosis (1 paper, 2025). Increased lipid within the cytoplasm of cells. "Individuals with severe steatosis (CAP > 290 dB/m) had markedly higher ORM2 levels (312.3 ng/mL) compared to those with normal CAP scores (210.4 ng/mL; p < 0.001)." (PMID 40943248, 2025). "ORM2 was identified as an independent predictor of steatosis severity and after adjusting for several metabolic variables (AOR = 1.005; 95% CI: 1.002–1.007)." (PMID 40943248, 2025). "Furthermore, the current study showed that individuals with severe steatosis (CAP > 290) had markedly higher ORM2 levels compared to those with normal CAP scores." (PMID 40943248, 2025).
cancer (14 papers, 2012 to 2024). A tumor composed of atypical neoplastic, often pleomorphic cells that invade other tissues. "In this preliminary research, we reported ORM2 as a new member of these cancer-associated glycoproteins." (PMID 22363757, 2012). "Other genes that are differentially regulated with a high median fold change include Orm2, an acute phase reactant, Cfd involved in the complement cascade, and Egfr a tyrosine kinase, which is upregulated in a number of different cancer types." (PMID 35203502, 2022). "Acute-phase response (APR) proteins such as Orm2 and Orm3 play an important role in anti-inflammatory and immunomodulatory responses that are initiated against infections, physical trauma, or malignancies." (PMID 34517344, 2021). "On the contrary, the expression level of ORM2 (Alpha-1-acid glycoprotein 2) was higher in advanced polyp and cancer than a polyp." (PMID 31749922, 2019). "The ninth introduced protein is ORM2 that is up-regulated in the polyp and cancer relative to the normal and polyp, respectively." (PMID 31749922, 2019). "The results of clinical pathological index analysis showed that serum ORM2 levels positively correlated with cancer progression." (PMID 25965830, 2015). "During the organization of our data, we found several serological glycosylated proteins like ORM2, EpCAM changing in levels during cancer development." (PMID 22363757, 2012). "The results showed that expression level of ORM2 in CRC cancer tissues was found to be higher than in normal tissue." (PMID 22363757, 2012). "When protein expression was measured by densitometer, the median densitometer value of ORM2 in CRC cancer tissues was significantly greater than that in corresponding adjacent normal mucous tissues (P<0.01)." (PMID 22363757, 2012). "There are several reports of ORM2 in intestinal system disease and cancers." (PMID 22363757, 2012). "Several other acute-phase response proteins were also elevated towards diagnosis (e.g., HP, ORM1, ORM2, CRP, SERPINF2), presumably due to a host systemic inflammatory response—a known prognostic indicator in cancer patients." (PMID 29232830, 2017). "Other markers (Alpha-1-acid glycoprotein 2 (ORM2), Alpha-1B-glycoprotein (A1BG), Haptoglobin (HP), and Leucine-rich alpha-2-glycoprotein (LRG1), etc.)were found to create an ambiguous core involved in cancer development but also to exactly promote tumor progression in the early stages." (PMID 32023884, 2020). "Out of the 236 cases, 177 cases (75%) had lower ORM2 protein expression in HCC tissues compared with their corresponding non-tumorous liver tissues, 49 (20.76%) cases had similar expression, and only 10 (4.24%) HCC patients had higher expression in cancer tissues." (PMID 25965830, 2015).
tumor (10 papers, 2011 to 2025). "As expected, we observed an increase in the levels of markers that are important for immune responses and inflammation (Saa1, Saa2, Lcn-2, Ltf, and Orosomucoid-2) and initiating and promoting tumor growth (Ighg1, Scube3, and Fgl1)." (PMID 33110211, 2020). "Collectively, our findings indicate that ORM2 is a functional downstream target of C/EBPβ and functions as a tumor suppressor in HCC." (PMID 25965830, 2015). "Histological examination of liver tissue sections indicated that tumor-bearing mice with ORM2 overexpression had fewer intrahepatic metastatic nodules than control mice (p < 0.05)." (PMID 25965830, 2015). "At the same time, we are also very interested in the function of ORM2 in the tumour progression owing to it regulates lipid homeostasis and protein quality control on the endoplasmic reticulum membrane." (PMID 22363757, 2012). "Thus, more details are needed to elucidate the mechanism of how ORM2 affects tumor growth and metastasis in HCC and its different functions in different tumors." (PMID 25965830, 2015). "This emerging evidence suggests that ORM2 may play important roles in tumor metastasis and progression." (PMID 25965830, 2015). "Moreover, the ectopic overexpression of ORM2 decreased HCC cell migration and invasion in vitro and intrahepatic metastasis in vivo, whereas silencing ORM2 expression resulted in increased tumor cell migration and invasion in vitro." (PMID 25965830, 2015). "Furthermore Orosomucoid 2 (ORM2) another plasma protein whose specific function has not yet been determined and not linked to carcinogenesis was found to be regulated in 25 tumor tissues." (PMID 21718500, 2011). "Orm2 is frequently down-regulated in HCC tissues and negatively correlates with tumor progression and intrahepatic metastasis." (PMID 34517344, 2021). "The urine protein levels of LRG1 were higher in patients with AOSD than in patients with RA or neoplasms and HC subjects, and the urine protein levels of ORM1 and ORM2 in AOSD patients were dramatically higher than those in patients with RA, neoplasms, or infections and HC subjects." (PMID 33013889, 2020). "The MFP proteome was enriched for several immune-related and plasma proteins more indicative of inflammatory infiltration and chronic immune activation rather than tumor-specific remodeling including C1QB, CFH, MZB1, IGKV3-20, ORM2, ALB, and AZGP1." (PMID 41007761, 2025). "MTT and colony formation assays indicated that ORM2 had no notable effect on HCC cell growth in vitro, while ORM2 overexpression obviously repressed orthotopic tumor growth in vivo." (PMID 25965830, 2015).
infection (4 papers, 2011 to 2023). The state of being infected such as from the introduction of a foreign agent such as serum, vaccine, antigenic substance or organism. "Increased expression of several acute-phase reactants, such as amyloid A proteins (Saa1, Saa2, Saa3), amyloid P component serum (Apcs), haptoglobin (Hp), hemopexin (Hpx) and orosomucoid 2 (Orm2), was observed only in CerS2-null mice after transfer of iNKT cells and infection with LCMV." (PMID 29163475, 2017).
colorectal (1 paper, 2012). "This may serve as a potential mediator of immune escape in CRC and the detection of ORM2 may be significant in distinguishing colorectal carcinogenesis from IBD." (PMID 22363757, 2012).
metabolic disease (1 paper, 2025). A congenital disorder (due to inherited enzyme abnormality) or acquired (due to failure of a metabolically important organ) disorder resulting from an abnormal metabolic process. "Future studies should adopt longitudinal designs to elaborate on the causal relationship between ORM2 levels and metabolic disease progression." (PMID 40943248, 2025). "Longitudinal studies are needed to clarify whether elevated ORM2 precedes disease onset or results from metabolic disorders." (PMID 40943248, 2025). "Thus, this study contributes additional evidence confirming the involvement of ORM2 in metabolic pathogenesis, enhancing the current understanding of biomarkers for metabolic diseases." (PMID 40943248, 2025).
ORM2 also shares sentences with these, for which no sentence is quoted: cholangiocarcinoma (2 papers); Cirrhosis (2); colorectal cancer (2); adult-onset Still disease (1); allergic rhinitis (1); autoimmune thyroiditis (1); colon cancer (1); colorectal adenocarcinoma (1); diabetes (1); endometrial cancer (1); endometriosis (1); endothelial dysfunction (1); hyperlipidemia (1); hyperplastic polyp (1); infectious disease (1); kidney cancer (1); kidney disease (1); liver inflammation (1); meningioma (1); non-alcoholic fatty liver (1); pancreatic ductal adenocarcinoma (1); pancreatitis (1); Parkinson disease (1); primary biliary cholangitis (1); psoriasis (1); renal fibrosis (1); varicocele (1).